LINC00244 (long independently transcribed non-coding RNA 244)
Synonyms: C7orf4; NCRNA00244
Gene: Long non-coding RNA gene on chromosome 7 (156,540,491 to 156,541,103, forward strand). Ensembl gene ENSG00000279418.
Diseases named in the same sentence as LINC00244 in open-access papers:
LINC00244 is named in the same sentence as 2 diseases in open-access papers, as found by Europe PMC text mining. Sharing a sentence is not in itself a finding about the gene and the disease.
LINC00244 shares sentences with these, for which no sentence is quoted: cutaneous melanoma (1 paper); hepatocellular carcinoma (1).